DTD2 (D-aminoacyl-tRNA deacylase 2)
Description:
Deacylates mischarged D-aminoacyl-tRNAs (By similarity). Also deacylates mischarged glycyl-tRNA(Ala), protecting cells against glycine mischarging by AlaRS (By similarity). Probably acts by rejecting L-amino acids from its binding site rather than specific recognition of D-amino acids (By similarity). Catalyzes the hydrolysis of D-tyrosyl-tRNA(Tyr), has no activity on correctly charged L-tyrosyl-tRNA(Tyr) (By similarity). By recycling D-aminoacyl-tRNA to D-amino acids and free tRNA molecules, this enzyme counteracts the toxicity associated with the formation of D-aminoacyl-tRNA entities in vivo and helps enforce protein L-homochirality. In contrast to DTD1, deacylates L-Ala mischarged on tRNA(Thr)(G4.U69) by alanine-tRNA ligase AARS. Can deacylate L-Ala due to a relaxed specificity for substrate chirality caused by the trans conformation of the Gly-Pro motif in the active site. Also hydrolyzes correctly charged, achiral, glycyl-tRNA(Gly) in vitro, although in vivo EEF1A1/EF-Tu may protect cognate achiral glycyl-tRNA(Gly) from DTD2-mediated deacetylation (By similarity).
Synonyms: ATD; C14orf126; MGC9912
Tractability: PROTAC: its protein half-life has been measured.
Gene: Protein-coding gene on chromosome 14 (31,446,036 to 31,457,506, reverse strand). Ensembl gene ENSG00000129480.
Subcellular location: Cytoplasm
Subcellular location (Human Protein Atlas): Vesicles
Gene Ontology:
Molecular function: Ala-tRNA(Thr) deacylase activity; D-aminoacyl-tRNA deacylase activity; Gly-tRNA(Ala) deacylase activity; protein binding; D-tyrosyl-tRNA(Tyr) deacylase activity; aminoacyl-tRNA deacylase activity
Biological process: aminoacyl-tRNA metabolism involved in translational fidelity; tRNA metabolic process
Cellular component: cytoplasm
Genetic constraint (gnomAD): Loss-of-function variants: 12 observed, 13.57 expected, observed/expected ratio (o/e) 0.88, 90% interval 0.56 to 1.43. The upper end of that interval is the gene's LOEUF score, 1.43, which puts it in group 5 of 6, group 1 being the genes least tolerant of losing a copy. Missense variants: 170 observed, 183.69 expected, observed/expected ratio (o/e) 0.93, 90% interval 0.82 to 1.05. Synonymous variants: 59 observed, 67.16 expected, observed/expected ratio (o/e) 0.88, 90% interval 0.71 to 1.09.
Homologues: Orthologues: chimpanzee DTD2 (99% identical), macaque DTD2 (95% identical), rabbit DTD2 (93% identical), guinea pig DTD2 (90% identical), pig DTD2 (90% identical), dog DTD2 (90% identical), rat Dtd2 (85% identical), mouse Dtd2 (85% identical), zebrafish dtd2 (64% identical), tropical clawed frog dtd2 (61% identical). Paralogues in human: DTD1 (24% identical).